TRPV4 (transient receptor potential cation channel subfamily V member 4)
Diseases named in the same sentence as TRPV4 in open-access papers (continued):
Sharing a sentence is not in itself a finding about the gene and the disease.
cancer (continued). "Tumor-associated macrophage infiltration levels are positively correlated with TRPV4 expression in TCGA pan-cancer samples." (PMID 41465326, 2025). "Here, we focused on TRPV4’s contribution to the pain sensation during cancer development and its manifestation." (PMID 38730655, 2024). "In cancers, TRPV4 acts as a critical regulator of both matrix stiffness and EMT, influencing cell migration capability and cancer progression." (PMID 39517820, 2024). "TRPV4 levels are deregulated along the progression of several cancer types, including breast cancer." (PMID 38514727, 2024). "Regarding this, TRPV4 has been increasingly recognized, especially its possible role in suppressing cancer cell metastasis." (PMID 38730655, 2024). "In cancer-related pain, TRPV4 channels are directly activated due to the excessive generation of oxidative stress by-products (e.g., H2O2), acidification, and the release of mediators such as TNF-α by the tumor microenvironment." (PMID 38730655, 2024). "The VPAC/TRPV4/Ca2+ signaling axis has been confirmed to be related to gastric cancer and to promote cancer cell metastasis." (PMID 38505262, 2024). "As described, only three types of cancer pain (bone, perineural, and orofacial) models investigated to date have covered the description of multiple mechanisms sensitizing TRPV4 (interleukins, DNA demethylation, ERK1/2, and PAR-2)." (PMID 38730655, 2024). "Although preliminary, these findings have brought into view different approaches regarding TRPV4’s involvement in cancer pain." (PMID 38730655, 2024). "This review summarizes the role of TRPV4 in cancer etiology and cancer-induced pain mechanisms, as well as the current status of the clinical research." (PMID 38730655, 2024). "Although many studies have already addressed the role of other TRP channels, including TRPA1 and TRPV1, in the process of cancer pain development, our review mainly focused on TRPV4’s action, addressing the uniqueness of this protein." (PMID 38730655, 2024). "These functions highlight the diverse roles of the TRPV4 ion channel in various physiological systems and its potential as a therapeutic target for epithelial-related conditions, including various cancers." (PMID 39517820, 2024). "Further on, enhanced expression of TRPV4 receptors has been observed in cancer-induced bone pain (CIBP), perineural, and orofacial cancer models, indicating the involvement of TRPV4 in the sensation of cancer pain." (PMID 39517820, 2024). "The limited studies published to date encountered enhanced TRPV4 expression in cancer-induced bone pain (CIBP), perineural, and orofacial cancer models, increasing pain perception." (PMID 38730655, 2024). "TRPV4-induced changes in actin-based structures therefore impact deformability and rigidity of the cancer cells, in this way favoring their potential to metastasize." (PMID 38514727, 2024). "In the current review, we discuss the involvement of TRPV4 channels in the intricate process of cancer-induced pain." (PMID 38730655, 2024). "Interference of TRPV4 activation and levels leads to a more migratory phenotype, allowing cancer cells to acquire invasive and metastatic properties." (PMID 39517820, 2024). "Here, we focused on summarizing the role of TRPV4 in cancer etiology and cancer-induced pain mechanisms." (PMID 38730655, 2024). "Considering this, it is pertinent to investigate the processes through which TRPV4 is involved in cancer pain." (PMID 38730655, 2024). "As TRPV4’s role in neuropathic pain was already established, this was the first study to confirm that TRPV4 is also involved in cancer pain." (PMID 38730655, 2024). "This altered ion transport through TRPV4 channels is highly relevant to essential aspects of human cancer pathophysiology." (PMID 38730655, 2024). "Clinical research will need to assess the therapeutic potential of inhibiting TRPV4 and sc polarity to target cancer metastasis." (PMID 37369706, 2023).
cancer (continued). "In the circulatory system, when metastatic tumor cells are subjected to fluid shear force, TRPV4 channel is opened and changes cytoskeleton, thereby promoting the extravasation of cancer cells." (PMID 37369706, 2023). "Apart from having key roles in cancer cells, TRPV4 is also involved in the immune response, with special implications for innate immune cell function." (PMID 37762011, 2023). "Our research suggests that TRPV4 is a promising therapeutic target for preventing cancer metastasis." (PMID 37369706, 2023). "According to research, TRPV4 level is higher in cancer cells from stomach, lung, and colon but lower in those from esophagus and prostate." (PMID 37369706, 2023). "Similar to other mechanosensitive channels, TRPV4 has been reported to be involved in different types of cancer." (PMID 37762011, 2023). "TRPV4 elicits cancer progression through inhibition of the tumor suppressor PTEN and upregulation of Akt-ZEB1 signaling, which modulates EMT and aggressiveness, while its inhibition leads to cell cycle arrest and induction of apoptosis/autophagy." (PMID 37762011, 2023). "Abnormal expression of TRPV4 is involved in the occurrence, growth and metastasis in types of cancer." (PMID 37369706, 2023). "Recent studies have revealed that TRPV4 and intracellular calcium signaling are crucial to cancer metastasis." (PMID 37369706, 2023). "The reduction of cancer metastases can result from TRPV4 inhibition, which not only impacts the migration and invasion of tumor cells, but also prevents the adhesion to vascular endothelial cells." (PMID 37369706, 2023). "Immunohistochemical analysis revealed significant differential expression of TRPV4 in bladder and para-carcinoma tissues." (PMID 36830651, 2023). "TRPV4 plays an important role in regulating cancer metastasis in breast, endometrial, gastric, and colon cancers." (PMID 36499486, 2022). "Calcium-gated ion channels, such as transient receptor potential cation channel subfamily V member 4 (TRPV4), P2X purinoceptor 7 (P2X7), and Piezo1, have recently been implicated as integral components in mechanisms of cancer metastasis and cell death." (PMID 36080197, 2022). "Kaplan-Meier survival analysis indicated that the hypermethylation of TRPV1 in LAML and BLCA, TRPV4 in SARC and UCEC, TRPV5 in BLCA, TRPV2 in ACC, and SARC cancers was associated with a poor prognosis in most tumors." (PMID 35174089, 2022). "TRPV3 and TRPV5 were hypomethylated in most cancer types, while TRPV4 was hypermethylated (P <0.05)." (PMID 35174089, 2022). "In particular, we discuss the roles of Piezo1/2, TRPC1, TRPC5, TRPM2, TRPM4, TRPM7, TRPV2, and TRPV4 in mechanosensing and cancer metastasis." (PMID 36158191, 2022). "The involvement of TRPV4 has been reported for various types of cancer, such as breast, lung, colon, uterus, and stomach." (PMID 36143906, 2022). "In the following section, we provide an overview of how Piezo1/2, TRPC1, TRPC5, TRPM2, TRPM4, TRPM7, TRPV2 and TRPV4 affect cancer cell behavior." (PMID 36158191, 2022). "For example, TRPA1, TRPC1, TRPV4, TRPV5, and TRPV6 exhibited higher CNV amplification, while TRPV1, TRPV2, TRPV3, and TRPC3 exhibited frequent CNV loss in cancer." (PMID 35614079, 2022). "TRPV4 links calcium signaling to DDX3X activity, which is essential for cancer-associated EBV infections." (PMID 36619170, 2022). "Among these, TRPV4 has recently drawn significant attention for its potential role in calcium signaling and cancer research." (PMID 36143906, 2022). "TRP channels implicated in mechanotransduction mechanisms that regulate cancer cell migration, invasion and metastasis include, among others, TRPC1, TRPC5, TRPM2, TRPM7, TRPM4, TRPV2 and TRPV4." (PMID 36158191, 2022). "Taken together, our findings demonstrate that t-EVs induce abnormal angiogenesis via TRPV4 downregulation-mediated activation of Rho/Rho kinase/YAP/VEGFR2 pathways and suggest t-EVs and TRPV4 as novel targets for vascular normalization and cancer therapy." (PMID 35004649, 2021).
cancer (continued). "Despite increasing evidences that has indicated the critical roles of TRPV4 in the progression of various cancers, the potential involvement of TRPV4 in CRC metastasis is still not clear." (PMID 34814869, 2021). "To further evaluate the significance of TRPV4 as a prognostic marker in tumor patients, we performed univariate Cox regression analysis and Kaplan-Meier survival analysis using TCGA pan-cancer data." (PMID 34262942, 2021). "Recent studies have shown that TRPV4 plays a role in a number of different functions in the body, including cancer." (PMID 34262942, 2021). "The calcium permeable mechanosensitive ion channel, transient receptor potential vanilloid 4 (TRPV4), has many implications in cancer progression." (PMID 35004649, 2021). "To validate this result, we downloaded immune cell infiltration data from the ImmuCellAI database and performed a correlation analysis, obtaining the same result that TRPV4 expression was positively correlated with the level of TAMs in pan-cancer." (PMID 34262942, 2021). "We conducted a comprehensive assessment of TRPV4, revealing its potential cancer-promoting effect as well as its role as an indicator of patient prognosis." (PMID 34262942, 2021). "The role of TRPV4 in cancer metastases has been investigated in several model systems and TRPV4 has also been most thoroughly studied with respect to its mechanosensitive character along cancer progression." (PMID 34356643, 2021). "TRPV4 therefore seems to have a major role in several steps of the cancer progression through its mechanosensitive nature and ability to both respond and regulate the stiffness of the environment." (PMID 34356643, 2021). "The GSEA results revealed that TRPV4 participates in immune regulation-related pathways in pan-cancer such as immunoregulatory interactions between lymphoid and non-lymphoid cells, the adaptive immune system, and the innate immune system." (PMID 34262942, 2021). "We further explored TRPV4 gene alterations in TCGA pan-cancer samples using cBioPortal and observed that patients with UCEC and ACC presented high gene alteration frequencies, including mutations and amplifications." (PMID 34262942, 2021). "Mechanosensitive TRPV4 has been clearly linked with VEGF/VEGFR2 signaling and tumor angiogenesis, further indicating that TRPV4 can play a role in various processes that potentiate cancer cell invasion." (PMID 34356643, 2021). "To explore the influence of TRPV4 expression on the sensitivity of anti-cancer drugs, we divided the tumor cells into high- and low-TRPV4 groups and compared their IC50 values." (PMID 34262942, 2021). "In contrast, low TRPV4 expression was observed in only six cancer types, namely, ACC, KIRP, LIHC, PRAD, SKCM, and THCA." (PMID 34262942, 2021). "Like TRPV2, TRPV4 has also been connected to cancers through Rho GTPases that act as major mediators of mechanical signaling." (PMID 34356643, 2021). "We focused here on the Vanilloid TRP subfamily, in which some members are linked to cancer (TRPV1, 2, 6, recently described for TRPV4), and for which gain-of-function mutations are the cause of genetic diseases (TRPV4)." (PMID 32186440, 2020). "Calcium ions increased the expression of TRPV4 by VPAC1, CaSR, and Ca2+-activated K+ channels including SK1/3, IK1, and BK in other cancers, but the mechanism of overexpressed TRPV4 in EC still remained elusive." (PMID 33230171, 2020). "In contrast, in breast cancer, TRPV4 activity promoted cancer cell invasion, transendothelial migration and metastasis." (PMID 32887220, 2020). "Given previous findings from other types of cancer, we next verified that TRPV4 acted to instigate cell migration in EC via its effects on the actin cytoskeleton." (PMID 33230171, 2020). "Currently, limited evidence shows that TRPV4 plays opposite roles in either promoting or inhibiting cancer development in different cancer types." (PMID 31189890, 2019).
cancer (continued). "Our findings show that EVs from tumor cells transform normal endothelial cells to a tumor endothelial cell-like phenotype via downregulation of TRPV4 and identifies TRPV4 as an alternative target for tumor angiogenesis and cancer therapy." (PMID 31921855, 2019). "We herein reviewed the research focus on the relationship between TRPV4 and cancer, also explored the mechanism of TRPV4-mediated oncogenesis and the strategy that target TRPV4 for tumor metastasis." (PMID 31235786, 2019). "Specifically, we described how changes in AQP5 expression and TRPV4 intra-cellular localisation under hyper-osmotic stress depend on the culture condition of different type of cancer cells." (PMID 31551497, 2019). "Meanwhile, TRPV4 is aberrantly expressed in many tumors and strongly corelated with the prognosis of cancer." (PMID 31235786, 2019). "In summary, TRPV4 plays an important role in the proliferation and differentiation of cells, which further affects the progression of cancer." (PMID 31235786, 2019). "We have previously shown that transient receptor potential vanilloid 4 (TRPV4) is downregulated in TEC, and that pharmacological activation of TRPV4 channels normalizes the tumor vasculature and improves cancer therapy." (PMID 31921855, 2019). "Upregulation of TRPV4 is accompanied by changes of the cytoskeletal network, enhanced blebability and reduced cell stiffness, facilitating cancer metastasis through neighboring tissues." (PMID 29772843, 2018). "So far, TRPV4 in breast cancer cells has been shown to promote cancer cell extravasation and to be a marker of poor prognosis of several solid epithelial cancers." (PMID 29293584, 2018). "HC-067047, the selective TRPV4 antagonist, showed a reversal of cancer-induced mechanical hyperalgesia in rats." (PMID 29637027, 2018). "This was proposed to point to a role of TRPV4 channels in cancer cell extravasation by reducing cancer cell rigidity and improving the ability of cancer cells to infiltrate through the surrounding tissue." (PMID 29772843, 2018). "Non-cancer HaCaT cells also expressed functional TRPV4 channels as proven by patch-clamp and qRT-PCR." (PMID 29293584, 2018). "TRPV4 expression is directly suppressed by DNA methylation silencing with H. pylori infection in gastric epithelium, suggesting that TRPV4 methylation silencing could be a novel diagnostic and therapeutic target for HpD and other functional disorders and cancers." (PMID 27687509, 2017). "This indicates that cancer progression is accompanied by an increase in the TRPV4 expression, suggesting a possible link between TRPV4 overexpression and emergence of metastatic traits." (PMID 28530703, 2017). "The findings provide new insights into the role of TRPV4 in cancer extravasation putatively by reducing cell rigidity through controlling the cytoskeleton at the cell cortex." (PMID 27291497, 2016). "Taken together, this study supports a role for TRPV4 in metastasis by regulating cancer cell stiffness and cytoskeleton at the cell cortex." (PMID 27291497, 2016). "The findings provide, for the first time, new insights into the molecular and cellular basis of TRPV4 function in cancer metastasis." (PMID 27291497, 2016). "It is possible that TRPV4 physically and functionally collaborate with integrins in cancer cells and capable of triggering the signal transduction cascades that leads to the cell mobility." (PMID 27291497, 2016). "TRPV4 is a member of the TRP (transient receptor potential) superfamily of cation channels, which have been implicated in human diseases and cancer." (PMID 27291497, 2016). "First, we confirmed if TRPV4 overexpression has a role in human cancer cell proliferation by performing FACS analysis." (PMID 27291497, 2016). "Collectively, the data suggest that TRPV4 promotes cancer cell extravasation/transendothelial migration by reducing cell stiffness through regulation of the cell cortex/cytoskeleton proteins." (PMID 27291497, 2016).
cancer (continued). "Regulation of cell stiffness and cell cortex dynamics are putative modes of actions through which TRPV4 promotes cancer cell extravasation." (PMID 27291497, 2016). "Our findings revealed that TRPV4-expressing cancer cells are softer and that TRPV4-conferred cell deformability was associated with actin depolymerization, VASP phosphorylation and inversely correlated with the activation of ERM and Cofilin." (PMID 27291497, 2016). "The expression of TRPV1 decreased in low grade and even more in high grade carcinoma when compared with normal urothelium, while TRPV4 expression was unchanged in all samples." (PMID 24868547, 2014). "TRPV4 expression in all samples of high grade carcinoma was similar to TRPV4 expression in normal urothelium as well as in low grade carcinoma." (PMID 24868547, 2014). "In the low grade carcinoma, TRPV4 expression was stronger or equal to the expression of TRPV4 in the normal urothelium." (PMID 24868547, 2014). "Additionally, pre-exposure to high viscoelasticity equips cancer cells with a TRPV4-dependent mechanical memory via the Hippo pathway, ultimately enhancing cancer cell migration, extravasation, and colonization." (PMID 39849659, 2025). "Notably, TRPV2 is implicated in inducing the death of various cancer cell types; however, many studies also indicate that the action of CBD is also mediated by the receptors TRPV1, TRPV4, CB1, CB2, and VDAC1." (PMID 40006844, 2025). "Although research on the potential role of TRPV4 in cancer metastasis is still in its early stages, the current research foundation could pave the way for further investigations into the involvement of TRPV4 in cancer pathogenesis." (PMID 40078961, 2025). "This understanding paves the way for developing diagnostic and prognostic strategies that leverage the selective intracellular localization patterns of TRPV4 and other mechanosensitive ion channels, ultimately guiding clinical decisions for patients with high-risk DCIS and other cancers." (PMID 40256993, 2025). "Moreover, a limited number of studies have investigated the TRPV4 channel’s involvement in cancer-induced pain." (PMID 38730655, 2024). "TRPV4 promotes the cancer malignant potential through NFAT4 signaling." (PMID 39822413, 2024). "Abnormal biophysical signaling may thus favor cancer progression through altered signaling via TRPV4 with other cooperative ion channels, and this should be more thoroughly explored in the future." (PMID 38514727, 2024). "TRPV4 induces protein kinase activity that regulates cancer cell growth via activation of AKT." (PMID 39759147, 2024). "Moreover, emerging evidence suggests that TRPV4 plays a crucial role in the autophagy phenomenon, complicating the cancer landscape and impacting the oncological patient prognostics." (PMID 38730655, 2024). "We speculate that the distinct role of TRPV4 in EMT may be due to the different metastatic propensity of types of cancer cells." (PMID 37369706, 2023). "Ca2+ influx mediated by TRPV4 may help to enhance cancer cell proliferation and other important processes in tumor progression, such as angiogenesis." (PMID 37762313, 2023). "Due to the diverse functions in which TRPV4 intervenes in cancer progression as well as its overexpression compared to healthy tissue, TRPV4 could be a potential pharmacological target with therapeutic benefits in different types of cancer." (PMID 37762011, 2023). "Additionally, TRPC1, TRPC5, TRPM2, TRPM4, TRPM7, TRPV2 and TRPV4 can independently induce EMT in cancer cells." (PMID 36158191, 2022). "In addition, TRPV4 is increasingly being considered a potential target for cancer therapy, especially in tumor metastasis prevention." (PMID 36499486, 2022). "TRPV4 was reported to play crucial roles in maintaining structural integrity of multiple tissues, and its regulatory role in diverse pathological processes in various cancers has been well documented." (PMID 35140788, 2022).